NOD2 (nucleotide binding oligomerization domain containing 2)
Diseases named in the same sentence as NOD2 in open-access papers (continued):
Sharing a sentence is not in itself a finding about the gene and the disease.
fungal infection (2 papers, 2018 to 2025). "Bioluminescence imaging revealed that Nod2−/− mice rapidly cleared the luciferase-expressing Aspergillus, whereas WT mice developed a fungal infection as indicated by a significantly higher luminescence signal on day 3 post infection (pi)." (PMID 29980664, 2018). "Moreover, NOD1 and NOD2 can also compete for downstream molecules, such as RIP2 or CARD9, that are also useful for other pathways important to fight fungal infections, such as Dectin-1, Dectin-2 (CLEC6A), and RIG-I (DDX58), leading to the induction of a tailored immune response." (PMID 41249509, 2025).
HCMV infection (2 papers, 2014 to 2016). "Since our results show that NOD2 mutation (3020insC) results in enhanced HCMV replication, it is possible that NOD2, a susceptibility gene for Crohns's disease, may influence susceptibility to HCMV infection." (PMID 24671169, 2014). "The combination of HCMV and MDP resulted in enhanced induction of NOD2 mRNA, compared to the induction achieved with HCMV infection or MDP alone." (PMID 26830977, 2016). "HCMV infection of human foreskin fibroblasts induced NOD2, the downstream receptor-interacting serine/threonine-protein kinase 2 (RIPK2), resulting in phosphorylation of TANK-binding kinase 1 (TBK1) and interferon regulatory factor 3 (IRF3)." (PMID 26830977, 2016). "NOD1 and NOD2 transcripts were quantified starting from the time of HCMV infection and then at 2, 4, 6, 8, and 24 hpi." (PMID 24671169, 2014). "In addition, mRNA induction of MDA5 or RIG-I following HCMV infection was similar between control and NOD2 knockdown cells, and MDP treatment resulted in less than 2-fold induction of these mRNA, indicating again its specific effects through NOD2." (PMID 26830977, 2016).
kidney (2 papers, 2019 to 2022). "NOD1 and NOD2 can be detected in various prostate lesions, including prostatic intraepithelial neoplasia (PIN), phyllodes-like tumors, and adenocarcinoma in transgenic adenocarcinoma of the mouse prostate (TRAMP)." (PMID 35846769, 2022).
Lewis lung carcinoma (2 papers, 2020 to 2022). "This compound, like DY-16-43 showed the highest level of antagonistic activity via MDP activating NOD2 signaling but has poorer solubility under the conditions tested.HEK-Blue hNOD2 cells; Lewis lung carcinoma (LLC) tumor-bearing mice." (PMID 36237313, 2022). "However, another study showed that NOD2 antagonist inhibited both NF-κB and MAPK inflammatory signaling, and played an adjuvant role to paclitaxel (PTX) to suppress Lewis lung carcinoma (LLC) growth." (PMID 32144252, 2020).
lung adenocarcinoma (2 papers, 2021 to 2023). A carcinoma that arises from the lung and is characterized by the presence of malignant glandular epithelial cells. "Here, we investigated that decreased NOD2 expressions could affect the phenotypic polarization of tumour‐associated macrophages and thus lead to the poor prognosis of lung adenocarcinoma patients." (PMID 34268854, 2021). "Further analysis clarified that V. parvula promoted activation of the NF-κB pathway via Nod2/CCN4 signaling, which promoted lung adenocarcinoma cell proliferation." (PMID 37452162, 2023). "Thus, V. parvula mediates activation of the Nod2/CCN4/NF-κB signaling pathway to promote non-small cell lung adenocarcinoma progression, thereby providing a potential target for diagnosing and treating lung adenocarcinoma." (PMID 37452162, 2023).
malignant glioma (2 papers, 2022 to 2025). A grade III or grade IV glioma arising from the central nervous system. "Our analysis revealed a marked upregulation of NOD2 transcript levels in GBM specimens (n = 153) relative to normal brain parenchyma (n = 5), indicating aberrant NOD2 activation in malignant gliomas." (PMID 40868292, 2025).
malnutrition (2 papers, 2023 to 2026). Inadequate nutrition resulting from poor diet, malabsorption, or abnormal nutrient distribution. "NOD2 activation has shown promise with aiding malnutrition recovery, lessening irritable bowel disease (IBD) symptoms, and increasing the efficacy of cancer immunotherapy." (PMID 41528771, 2026).
Myalgia (2 papers, 2024 to 2025). "Patients with combined NOD2 and MEFV variants were identified in 4 patients who experienced a higher proportion of headaches (75% vs. 9.1%), chest pain (50% vs. 9.1%), myalgia (75% vs. 36.4%), and weight loss (50% vs. 36.4%)." (PMID 39290705, 2024).
myocardial ischemia (2 papers, 2018 to 2021). A disorder of cardiac function caused by insufficient blood flow to the muscle tissue of the heart. "It has been indicated that NOD2 can contribute to myocardial ischemia/reperfusion injury through inducing cardiomyocyte apoptosis and inflammation." (PMID 34925465, 2021). "In myocardial ischemia/reperfusion injury, TIPE2 inhibits nucleotide-binding oligomerization domain-containing protein 2 (NOD2), activates mitogen-activated protein kinases MAPK and NF-κB signaling, and negatively regulates NOD2-mediated inflammatory signaling." (PMID 30586922, 2018).
non-small cell lung adenocarcinoma (2 papers, 2023 to 2025). Type of epithelial lung cancer arising from glandular origin. "V. parvula mediates activation of the Nod2/CCN4/NF-κB signaling pathway to promote non-small cell lung adenocarcinoma progression." (PMID 40391224, 2025). "Furthermore, Veillonella has been associated with activation of tumor-promoting pathways, including PI3K and the Nod2/CCN4/NF-κB axis, which may contribute to inflammatory responses and proliferation in non-small cell lung adenocarcinoma." (PMID 40391224, 2025).
Opportunistic infection (2 papers, 2014 to 2025). An infection that is caused by a pathogen that would generally not be able to cause an infection in a host with a normal immune system. "Thus we suggest to specifically include reactivated and opportunistic infections in the differential diagnosis of suspected catheter related infection in patients with intestinal failure who carry mutations in their NOD2 gene." (PMID 24597572, 2014).
pancreatitis (2 papers, 2014 to 2016). Inflammation of the pancreas. "As for AP, some known extracellular NLRP3 activators like DNA, adenosine triphosphate (ATP), high mobility group box 1 (HMGB1), and nucleotide binding oligomerization domain 2 (NOD2) are all associated with the inflammation during the development of pancreatitis." (PMID 25214720, 2014).
pericarditis (2 papers, 2019 to 2024). An inflammatory process affecting the pericardium. "Eleven variants were located in genes already associated with recurrent pericarditis (NLRP3, TNFRSF1A and MEFV) and five in inflammation/immunodeficiency-related genes (IFIH1, NFKBIA, JAK1, NOD2 and ALPK1)." (PMID 39347728, 2024).
Pleuritis (2 papers, 2022 to 2024). Inflammation of the pleura. "This allele significantly reduced the SPES score on farm B. The NOD2-2197C allele might enhance the response to the gram-negative bacteria A. pleuropneumoniae cell body, thus mitigating pleuritis symptoms." (PMID 36428390, 2022). "NOD2 and TLR5 SNPs were associated with pleuritis, whereas NLRP3 SNPs were associated with an index of mycoplasmal pneumonia." (PMID 36428390, 2022).
pneumococcal pneumonia (2 papers, 2015 to 2023). A febrile disease caused by STREPTOCOCCUS PNEUMONIAE. "Here we set out to determine the contribution of NOD2 to the host response during pneumococcal pneumonia by infecting NOD2 deficient (Nod2-/-) mice with a variety of wild-type (Wt) and genetically modified S. pneumoniae strains via the airways." (PMID 26673231, 2015). "In the present study we aimed to characterize the in vivo relevance of NOD2 in pneumococcal pneumonia." (PMID 26673231, 2015). "To evaluate a functional role for NOD2 in pneumococcal pneumonia, we first assessed the capacity of neutrophils and alveolar macrophages, the main cell types involved in pulmonary clearance of S. pneumoniae, to internalize this pathogen in vitro." (PMID 26673231, 2015). "Together these data suggest that NOD2, while contributing to antibacterial defense against normally avirulent pneumococci, does not play a significant role in the innate immune response during pneumococcal pneumonia in vivo." (PMID 26673231, 2015). "Thus, to validate our findings of the limited role of NOD2 in host defense during pneumococcal pneumonia, we performed additional studies with the highly virulent serotype 3 S." (PMID 26673231, 2015).
pouchitis (2 papers, 2021 to 2022). Acute inflammation in the intestinal mucosa of the continent ileal reservoir (or pouch) in patients who have undergone ileostomy and restorative proctocolectomy (proctocolectomy, restorative). "From a genetic perspective, some polymorphisms hitting IL-1RA, TNFalpha, TLR9, and NOD2/CARD15 were associated with an increased risk of pouchitis." (PMID 34831464, 2021). "A reduced level of this potentially ‘beneficial’ bacteria was found in one NOD2 positive sibling who developed pouchitis, while a normal Faecalibacterium prausnitzii level was found in his brother and mother, who remained pouchitis-free after IPAA surgery." (PMID 34831464, 2021).
preeclampsia (2 papers, 2008 to 2014). Preeclampsia is a hypertensive disorder of pregnancy that is characterized by new-onset hypertension with proteinuria presenting after 20 weeks of gestation, and depending on mild or severe forms may initially present with severe headache, visual disturbances, and hyperreflexia. "Combined positivity for any of the TLR-4 and NOD2 allelic variants and high levels of IL-6 were 6.9-fold more common in women with a history of early-onset preeclampsia than in healthy pregnant women (OR 6.9)." (PMID 24991435, 2014). "Combined positivity for any of the TLR4 and NOD2 allelic variants and high levels of interleukin-6 was 6.9-fold more common in women with a history of early-onset preeclampsia (95% CI 2.1–23.2) compared to controls." (PMID 18382655, 2008). "We observed an association of common TLR4 and NOD2 gene variants, and pro-inflammatory phenotype with a history of early-onset preeclampsia and HELLP syndrome." (PMID 18382655, 2008). "In this study, a significant association was observed with NOD2 polymorphisms in women with preeclampsia, mostly late-onset disease, by a global haplotype-based approach." (PMID 18382655, 2008). "In this study we examined the contribution of two common allelic variants of the TLR4 (D299G and T399I) and three common allelic variants of NOD2 (R702W, G908R and L1007fs) to the pathogenesis of early-onset preeclampsia and HELLP syndrome." (PMID 18382655, 2008). "We hypothesized that allelic variants of TLR4 and NOD2, as well as high circulating levels of pro-inflammatory biomarkers after delivery would relate to a history of early-onset preeclampsia and HELLP syndrome." (PMID 18382655, 2008). "We determined five common mutations in TLR4 (D299G and T399I) and NOD2 (R702W, G908R and L1007fs) in 340 primiparous women with a history of early-onset preeclampsia, of whom 177 women developed HELLP syndrome and in 113 women with a history of only uneventful pregnancies as controls." (PMID 18382655, 2008). "Nonetheless, increasing tertiles of interleukin-6 and fibrinogen levels were associated with higher odds ratios for early-onset preeclampsia in women carrying one or more TLR4 or NOD2 mutations, compared to women with the wild-type TLR4 or NOD2 genotype." (PMID 18382655, 2008). "Individually, each of the NOD2 allelic variants (R702W, G908R and L1007fs) did not contribute to the development of early onset preeclampsia with or without HELLP syndrome." (PMID 18382655, 2008). "We examined whether allelic variants of the innate immune receptors Toll-like receptor 4 (TLR4) and nucleotide-binding oligomerization domain 2 (NOD2), that impair the inflammatory response to endotoxin, are related to preeclampsia and HELLP syndrome." (PMID 18382655, 2008).
pulmonary hypertension (2 papers, 2018 to 2021). Increased pressure within the pulmonary circulation due to lung or heart disorder. "Compared to wild-type mice, NOD2-deficient mice developed severe pulmonary hypertension with exaggerated elevation of right ventricular systolic pressure, profound right ventricular hypertrophy and striking vascular remodeling after exposure to hypoxia." (PMID 29560100, 2018).
pulmonary tuberculosis (2 papers, 2007 to 2012). A bacterial infection that affects the lungs and is caused by Mycobacterium tuberculosis. "To further define a role for NOD2 in disease pathogenesis, we analysed NOD2 mRNA transcriptional responses in pulmonary leucocytes and PBMCs harvested from patients with pulmonary tuberculosis (PTB) and healthy controls." (PMID 17705850, 2007). "We analysed NOD2 mRNA expression by real-time polymerase chain-reaction in alveolar lavage cells obtained from 15 patients with pulmonary tuberculosis and their matched controls." (PMID 17705850, 2007). "To further define a role for NOD2 in disease pathogenesis, we analysed NOD2 transcriptional responses in pulmonary leucocytes and mononuclear cells harvested from patients with pulmonary tuberculosis (PTB)." (PMID 17705850, 2007).
renal fibrosis (2 papers, 2014 to 2017). A final common manifestation of a wide variety of chronic kidney diseases characterized by glomerulosclerosis and tubulointerstitial fibrosis. "However, infected kidneys from Nod1/2dko mice exhibited interstitial fibrosis, therefore excluding a role for both Nod1 and Nod2 in the induction of renal fibrosis." (PMID 24498450, 2014). "Compared to infected WT mice, no reduction in Leptospira-induced fibrosis was observed in kidneys of either Nod1/2dko or Casp1ko mice, showing that Nod1, Nod2 and NLRP3 are not involved in the Leptospira-induced renal fibrosis." (PMID 24498450, 2014). "Since TLRs seem not to be involved in Leptospira-induced renal fibrosis, we wondered whether other innate immune receptors from the NLR family, such as the cytosolic Nod1, Nod2, and NLR3 receptors, could be involved." (PMID 24498450, 2014).
respiratory syncytial virus infection (2 papers, 2020 to 2024). "NOD-containing protein 2 (NLRC2, also known as NOD2) has been demonstrated to recognize viral genomic ssRNA during respiratory syncytial virus infection and instigate IRF3-dependent antiviral responses via MAVS." (PMID 39143032, 2024). "During respiratory syncytial virus infection, NOD2, but not NOD1, can sense single-stranded RNA (ssRNA) from the virus and interacts with mitochondrial antiviral signaling (MAVS)." (PMID 32778560, 2020).
sacroiliitis (2 papers, 2010 to 2021). "Non-HLA polymorphisms such as nucleotide-binding oligomerization domain-containing protein 2 (NOD2) polymorphisms increase the risk of CD about 4–40 times and is associated with sacroiliitis amongst patients with IBD." (PMID 34604268, 2021).
SAPHO syndrome (2 papers, 2020 to 2025). SAPHO syndrome (acronym for Synovitis, Acne, Pustulosis, Hyperostosis and Osteitis) is an auto-inflammatory disease, mainly characterized by the association of neutrophilic cutaneous involvement and chronic osteomyelitis. "Several other genes, such as PSTPIP2, NOD2, and LPIN2, have been found to be associated with SAPHO syndrome, although have yet to be confirmed pathogenic." (PMID 33153463, 2020).
short gut syndrome (2 papers, 2014). "They reported that NOD2 gene variants were associated with increased liver and intestinal failure in patients with short-gut syndrome." (PMID 24393249, 2014).
tenosynovitis (2 papers, 2014 to 2022). Inflammation of the synovial lining of a tendon sheath. "The reasons for this absence of canonical features of inflammation in the presence of synovial inflammation, along with the predominance of tenosynovitis, caused by NOD2 mutations are intriguing research questions in understanding the molecular mechanisms of inflammation." (PMID 24713464, 2014).
Yersinia infection (2 papers, 2008 to 2009). "In order to further confirm the role of Nod2 in the susceptibility to Yersinia infection, we used an additional mouse model carrying the mutation homologous to the CD associated frame-shift mutation 1007fs (Nod2mt/mt)." (PMID 18648508, 2008). "Nod2−/− mice were also characterized by no change in the proportion of CD3+ T-cells in comparison to the basal (non infected) level, while Nod2+/+ mice showed an increased level of CD3+ T-cells after Yersinia infection." (PMID 18648508, 2008). "We hypothesized that Nod1 and/or Nod2 could be involved in NFκB activation in response to Yersinia infection, as peptidoglycan fragments could have access to the host cell cytosol via the T3SS." (PMID 19997504, 2009). "Thus, the negative role of Nod2 observed after Yersinia infection appears to be the exception rather than the rule." (PMID 18648508, 2008).
adenoma (1 paper, 2023). A neoplasm arising from the epithelium. "Loss of Nod2 signaling in myeloid cells contributes to tissue repair in the inflamed large intestine and decreases adenomas through a lysozyme-dependent mechanism." (PMID 37876927, 2023).
Airway obstruction (1 paper, 2020). Obstruction of conducting airways of the lung. "NOD2/CARD15 mutations may lead to an altered microbial composition resulting in an increased susceptibility to subclinical pulmonary infections, dysregulated and prolonged inflammation, bronchial epithelial injury and finally airway obstruction." (PMID 33424849, 2020).
ANCA-associated vasculitis (1 paper, 2022). "Unlike systemic sarcoidosis, JIA, CGD, ANCA-associated vasculitis and granuloma forming infections, NOD2 mutation is associated with chronic inflammatory disorders such as BS/EOS and CD." (PMID 36192768, 2022).
aphthous ulcers (1 paper, 2025). "Increased levels of transcripts for monocyte‐specific genes (e.g. CD14, NOD2, S100A8/A9; Clusters 8 and 14) indicate specific infiltration of these cells into the aphthous ulcers." (PMID 40386941, 2025).
aspergillosis (1 paper, 2018). Aspergillosis is an infection, growth, or allergic response caused by the Aspergillus fungus. "Considering recent evidence suggesting a crucial role for the autophagy machinery in host defence against Aspergillus25, NOD2 is a candidate susceptibility gene for aspergillosis." (PMID 29980664, 2018). "Crucially, Nod2 deficiency results in resistance to Aspergillus infection in an in vivo model of pulmonary aspergillosis." (PMID 29980664, 2018). "Nod2-deficient mice were resistant against aspergillosis despite being immunosuppressed and showing severe symptoms of aspergillosis such as weight loss, hunching, head tilting, and circling." (PMID 29980664, 2018). "A previous study also investigated NOD2 polymorphisms in association with aspergillosis in HSCT patients." (PMID 29980664, 2018). "Since NOD2 genetic variation was associated with a reduced risk of IA, the impact of full Nod2 deficiency on susceptibility to aspergillosis was validated in an experimental model of IA." (PMID 29980664, 2018). "In the HSCT patients, the NOD2 P268S polymorphism was only associated with a reduced incidence of aspergillosis in the donor genotype." (PMID 29980664, 2018). "NOD2 deficiency mediates protection against Aspergillus in mice, and polymorphisms in NOD2 alter the susceptibility of HSCT patients to develop aspergillosis." (PMID 29980664, 2018). "Additionally, it is unknown whether defective NOD2 signalling influences susceptibility to aspergillosis." (PMID 29980664, 2018). "Although previous studies have revealed enhanced expression of NOD2 during aspergillosis and synergism with Aspergillus-induced cytokine responses, these studies did not thoroughly investigate whether NOD2 modulates anti-Aspergillus host defence." (PMID 29980664, 2018). "However, thorough investigation of the impact of NOD2 on susceptibility to aspergillosis is lacking." (PMID 29980664, 2018).